NOD1 (nucleotide binding oligomerization domain containing 1)
Diseases named in the same sentence as NOD1 in open-access papers (continued):
Sharing a sentence is not in itself a finding about the gene and the disease.
infection (continued). "SK3842 infection raised Nod1 and repressed MyD88 levels in differentiated Caco-2 but did not have any significant effect on Nod1 and MyD88 in SC-rich CD44high cells from infected culture, further confirming that only non-stem cells are responsive to SK3842 invasion." (PMID 28300841, 2017). "This new study provides evidence for an alternative NOD1-dependent signalling pathway, which activates the IRF3 and IRF7 transcription factors to induce the production of type I IFNs that are required for Hp-specific cytokine and chemokine responses, and infection control." (PMID 28272373, 2017). "Nine out of 12 Nod1−/− mice survived, whereas 12 out of 13 WT mice did not survive the infection." (PMID 29326692, 2017). "Similarly, infection of murine macrophages with murine norovirus-1 (MNV1) induced NOD1 and NOD2 in an IFN-β-dependent manner, and subsequent bacterial infection enhanced activation of NOD1/2, mediated by type I IFNs34." (PMID 26830977, 2016). "Why lethal Ehrlichia infection highly increase Nod1 expression early in infection is not yet clear." (PMID 23526993, 2013). "However, NOD1, NOD2, and Rip2 knockout mice were no more susceptible to infection with virulent B. abortus than wild-type mice." (PMID 22203860, 2012). "In addition, NOD1 and NOD2 may be activated by PGN fragments, introduced into host cells during infection by pathogens that possess auxiliary secretion systems." (PMID 17397264, 2007). "Given that many pathogens induce ER stress and that peptidoglycan-free viruses and parasites activate NOD1 and/or NOD2-dependent inflammation, it is reasonable to speculate that NOD1 and/or NOD2 are activated by sensing the ER stress and possibly SAMPs during these infections." (PMID 34201509, 2021). "In this review, we will focus on functional aspects of the NOD1 and NOD2 proteins and discuss recent findings related to their roles in microbial recognition and the induction of inflammatory responses that lead to the restriction of infections with bacterial and non-bacterial pathogenic microbes." (PMID 23162548, 2012). "Mice lacking both NOD1/NOD2 or RIP2, an adaptor protein of NOD1/NOD2, exhibited higher bacterial burdens after infection with Chlamydia and an NOD1/2-dependent TUDCA-sensitive inflammatory response." (PMID 32487756, 2020). "Compared to synthetic ligands iE-DAP and MDP, E. faecium with a multiplicity of infection (MOI = 1) activated NOD2, but not NOD1." (PMID 30969170, 2019). "By contrast, leptospires would not need to escape the recognition by NOD1 in humans because they avoid TLR4 recognition of their atypical LPS, potentially resulting in severe infection." (PMID 29211798, 2017). "The detection of endogenous TAK1 activation in HEK293T cells following infection with wildtype, but not T3SS3 mutants, suggests the activation of the intracellular pattern recognition receptors (PRRs) NOD1 and NOD2, both of which signal through TAK1." (PMID 24884837, 2014). "During “normal” infections, however, the T3SS-1-mediated invasion seems to outweigh the alternative invasion route, leaving NOD1 and NOD2 to play a non-significant role." (PMID 24381573, 2013). "Regardless of the roles of NOD1 and NOD2 in the immune response to certain microbes, for some bacterial pathogens, such as Coxiella burnetii and Brucella abortus, NOD1 and NOD2 play no role in restricting bacterial replication in murine models of infection." (PMID 23162548, 2012). "However, after multiple infections, TLR4 and TLR9 levels showed no change, MyD88 was diminished even further and Nod1 and its main adaptor protein, Rip2, were elevated significantly." (PMID 28300841, 2017).
tumor (90 papers, 2009 to 2026). "NOD1 absence was associated with tumor growth and cell proliferation induced by an increased sensitivity to estrogen in MCF-7 cells." (PMID 38602568, 2024). "We found that higher NOD1 expression was present in patients with LM, and was associated with massive macrophage infiltration, which facilitated tumour metastasis." (PMID 36068649, 2022). "NOD1 mutations are closely related to inflammatory diseases in humans, and a close relationship exists between inflammation and tumor." (PMID 35153782, 2022). "Other apoptosis-associated proteins, such as TFIP8, a tumor suppressor that regulates TNF-mediated apoptosis via inhibition of caspase-8 were also upregulated in HS578T/NOD1." (PMID 30791886, 2019). "In ER-positive MCF-7 cells, NOD1 deficiency correlates with tumor growth, an increased sensitivity to estrogen-induced cell proliferation and impaired Nod1-dependent apoptosis." (PMID 30837326, 2019). "In line with this, in vivo studies utilising a model of colitis-associated colon tumourigenesis revealed that NOD1-deficient mice are prone to develop inflammation-induced tumours." (PMID 28432285, 2017). "Studies have shown that Fusobacterium nucleatum can induce neutrophil extracellular traps (NETs) formation via the TLR4-ROS and NOD1/2 signaling pathways in neutrophils, accelerate tumor growth, and promote tumor metastasis, manifested as EMT-associated cell migration." (PMID 41019090, 2025). "NOD1 promotes the expansion of myeloid-derived suppressor cells and may influence tumor-associated disbiosis." (PMID 40659866, 2025). "Moreover, CRC patients whose primary tumour tissues had higher NOD1 levels, showed poorer prognoses and increased risk of LM." (PMID 36068649, 2022). "We also showed that EVs from the plasma of CRC‐LM patients significantly activated the NOD1 signalling pathway in human peripheral blood mononuclear cells (PBMCs), while elevated NOD1 expression in tumour tissues was consistently associated with poor prognosis in patients with CRC‐LM." (PMID 36068649, 2022). "Likewise, in ER-positive MCF-7 cells, NOD1 deficiency was found to be correlated with tumour growth, an increased sensitivity to estrogen-induced cell proliferation and impaired Nod1-dependent apoptosis." (PMID 33023525, 2020). "The overlapping gene NOD1, a gene implicated in the immune response that is known to obstruct bacterial invasion and initiate inflammation, as well as exert inhibitory effects on tumor cell viability and proliferation." (PMID 31969898, 2019). "Moreover, knockout of NOD1 in MCF7 cells leads to estrogen-dependent tumor growth in immune deficient mice, while its overexpression inhibits estrogen-dependent tumor proliferation in this model." (PMID 30791886, 2019). "Moreover, high NOD1 expression in tumour tissues is associated with poor prognosis of CRC‐LM." (PMID 36068649, 2022). "Considering that NOD1 was activated by EVs from CRC cells and the plasma of CRC‐LM, these results implied that high levels of NOD1 in tumour‐associated macrophages may be activated by tumour‐derived EVs to induce inflammatory responses, subsequently promoting LM." (PMID 36068649, 2022). "Mechanically, the tumor-derived CCL5 induced by L. intestinalis recruited DC chemotaxis through the NOD1/NF-κB signaling pathway." (PMID 39773173, 2025). "Taken together, these results suggested the NOD1/NF-κB pathway was involved in the secretion of CCL5 from tumor cells activated by L. intestinalis." (PMID 39773173, 2025). "By contrast, systemic NOD1 activation can expand MDSCs and sustain Arg1-dependent suppression, fostering tumor-permissive microenvironments in CRC models." (PMID 41339918, 2025).
tumor (continued). "Another upregulated PRG is nucleotide-binding oligomerization domain-containing protein 1 (NOD1), which is known to promote immunosuppression and tumor progression." (PMID 39062119, 2024). "NOD1 expression was considerably higher in pre-TNC tumor tissues from NR than in those from CR, as determined by immunohistochemistry (IHC)." (PMID 38437016, 2024). "Mechanically, through Bulk-RNA sequencing and experiments, we found that PANX1 promoted tumor progression and immune regulation via the ATP release to active NOD1/NFκB signaling pathway in PDAC." (PMID 39882247, 2024). "NOD1 also abrogates hepatocellular carcinoma proliferation and enhances the tumor response to chemotherapy." (PMID 38462600, 2024). "NOD1-overexpressing remarkably promoted tumor growth, and the ALDH+ BCSC percentage was elevated by 40%." (PMID 38437016, 2024). "The NOD1 group exhibited notably higher tumor volume and weight compared to the vector and MARCH7 groups." (PMID 38462600, 2024). "In the liver, tissues exposed to heat stress, the upregulated pathways comprised of IL-17 signaling, NOD1/2 signaling associated with liver injury, TREM1 signaling of hepatic inflammation, tumor microenvironment signaling, Th1 signaling, and eNOS signaling." (PMID 38719902, 2024). "Consistently, a limited dilution assay (LDA) showed that the frequency of tumor-initiating cells increased by 4-fold in the NOD1-overexpressing group, whereas NOD1-knockdown had the opposite effects." (PMID 38437016, 2024). "Intra-cellular activation of NOD1 in T cells enhances the production of the tumor-suppressing cytokine IFNγ, thereby inhibiting tumorigenesis." (PMID 38523155, 2024). "According to this theory, our data showed that eugenol administration decreased the expression of the NOD1-NF-κB pathway, which ultimately aided in the drug’s tumor-suppressing effects." (PMID 36923216, 2023). "The results showed that eugenol, as a natural compound, has significant anti-tumor effects on TNBC proliferation and metastasis, and probably played an anti-tumor role by influencing NOD1- NF-κB signal pathway." (PMID 36923216, 2023). "NOD1 inflammasomes enhances tumor cell adhesion, migration and metastasis by activating MAPK signaling pathway." (PMID 37020871, 2023). "A recent study has shown that NOD1 promotes immunosuppression and regulates pro‐tumour TIME by regulating myeloid cells stimulating MDSC amplification, and maintaining its immunosuppressive potential." (PMID 35083859, 2022). "We exploited a Gene Expression Omnibus (GEO) dataset (GSE41258) microarray gene file from patients with CRC and CRC‐LM to investigate the role of NOD1 in primary CRC tumour tissues to promote LM." (PMID 36068649, 2022). "NOD1 expression was increased in primary tumour and metastatic liver tissues compared to that in paired adjacent normal tissues; the elevated expression of NOD1 was closely related to massive macrophage infiltration." (PMID 36068649, 2022). "Consistent with results of the GSE41258 dataset analysis, NOD1 expression was markedly higher in primary tumour and metastatic liver than in the corresponding normal tissues, according to qPCR analysis of tissues from patients with CRC‐LM." (PMID 36068649, 2022). "Collectively, these findings indicated that high NOD1 expression in tumour tissues facilitates macrophage infiltration to promote metastasis in the liver and poor prognosis in CRC patients." (PMID 36068649, 2022). "NOD1 activation reportedly fosters an immunosuppressive tumour microenvironment to promote CRC development in both colitis‐associated carcinogenesis and spontaneous carcinogenesis." (PMID 36068649, 2022). "The high expression of NOD1 is related to the poor prognosis of patients, and the activation of NOD1 promotes the metastasis of tumor cells." (PMID 36186792, 2022).
tumor (continued). "During analysis of NOD1 expression in tumour and normal tissues from patients with CRC, we, and others, found that a single reference gene was not sufficiently accurate to quantify target genes." (PMID 36068649, 2022). "Comparison of NOD1 levels between primary tumour tissues and metastatic liver tissues revealed that NOD1 is upregulated in the metastatic liver." (PMID 36068649, 2022). "The high CDC42 cargo in CRC‐EVs was transported into macrophages, where it acquired its GTP‐bound active state and subsequently, mediated NOD1 activation, triggering the inflammatory response to promote tumour cell migration." (PMID 36068649, 2022). "For instance, a recent study has shown that activated NOD1 leads to the progression of colorectal carcinogenesis by modulating the immunosuppressive functions of tumor-infiltrating leukocytes via arginase-1 activity." (PMID 34066406, 2021). "Based on the verification of the tissues from COAD patients by the method of qPCR, the results showed that CASP4, CASP5, PRKACA, and NOD1 were expressed differentially between normal and tumor tissues." (PMID 34938319, 2021). "In our sample, we also found that the expression of NOD1 in tumor tissue is low and there are differences in different ages and stages." (PMID 32843657, 2020). "TCGA COAD data and human CRC tumor IHC demonstrate a significant survival trend between high NOD1 levels and lower overall survival." (PMID 31956962, 2020). "Correspondingly, in the same cells, NOD1 overexpression inhibited ER-dependent tumor growth and reduced estrogen proliferative response in vitro." (PMID 30837326, 2019). "In an in vivo subcutaneous xenograft model, Evo also exhibited excellent tumor inhibitory effects via the NOD1 signal pathway." (PMID 30384473, 2018). "We employed in vitro colony formation assays to infer tumor growth and viability of the NOD1/2-overexpressing populations." (PMID 29615116, 2018). "This study showed the relevance of interactions between TLR4, NLRP3 and NOD1 in LM-induced DC maturation and anti-tumor responses, which help us understand the immune regulatory mechanisms involved in LM vaccine-related tumor immunotherapy." (PMID 25826093, 2015). "In sharp contrast, mice grafted with NOD1-deficient MCF-7 cells displayed increased and continued tumor growth." (PMID 25071785, 2014). "Additionally, previous studies have revealed that NOD1 initiates the secretion of inflammatory cytokines and chemokines, which contribute to tumor development and progression." (PMID 40430095, 2025). "The results demonstrated that NOD1 expression varied between tumor and normal tissues." (PMID 41363048, 2025). "Thus, the functions and regulatory mechanisms of NOD1 in tumor progression need to be further elucidated, especially in different cancer types." (PMID 38437016, 2024). "Conflicting roles of NOD1 in tumor progression have been reported." (PMID 38437016, 2024). "Additionally, NOD1 accelerates tumorigenesis, tumor metastasis, and NOD2 expression in human squamous cervical cancer." (PMID 38462600, 2024). "More precisely, NOD1 exerts its anti-tumor effects through the induction of apoptosis, but uncontrolled apoptosis mediated by NOD1 might induce immunosuppression microenvironment, thereby promoting tumor progression." (PMID 37324457, 2023). "Therefore, NOD1 inflammasomes was considered to be a tumor suppressor in ER-positive breast cancer cells." (PMID 37020871, 2023). "To sum up, we found that eugenol may play its anti-tumor role by binding to NF-κB protein and inhibiting NOD1-NF-κB signaling pathway." (PMID 36923216, 2023). "NOD1 expression is upregulated in tumour tissues from all stages of CRC." (PMID 36068649, 2022). "Our findings suggest that CRC‐EVs activate NOD1 to promote tumour metastasis, thus, NOD1 may serve as a potential target in the diagnosis and treatment of CRC‐LM." (PMID 36068649, 2022).
tumor (continued). "Moreover, immunofluorescence analysis was conducted to observe NOD1 expression and macrophage infiltration in tumour and adjacent normal tissues from patients with CRC‐NLM." (PMID 36068649, 2022). "To investigate the potential of NOD1 to sense tumour cell‐derived EVs, we first determined whether NOD1 signalling is activated following treatment of macrophages with EVs from CRC cells." (PMID 36068649, 2022). "NOD1 was downregulated in tumor samples in our study and its high expression predicted better survival, which suggested that the NOD1 may be a tumor suppressor gene." (PMID 34627252, 2021). "In addition, tissue validation results also showed that CASP4, CASP5, PRKACA, and NOD1 were differentially expressed between tumor and normal tissues from COAD patients." (PMID 34938319, 2021). "ProEGCG, but not EGCG, elicited a significant decrease in the growth of the EC xenografts, promoted apoptotic activity of tumour cells in the EC xenografts, and decreased microvessel formation, by differentially suppressing anti-apoptotic molecules, NOD1 and NAIP." (PMID 33023525, 2020). "Irrespective of CRC stages, tumor cores were associated with increased NOD1 protein levels compared to that of paired normal adjacent tissues (Cochran-Mantel-Haenszel P < 0.0001)." (PMID 31956962, 2020). "Furthermore, according to the MTT assay, tumor cells with higher protein levels of NOD1, NOD2 and NF-κB had a relatively high growth rate." (PMID 32874130, 2020). "To confirm whether the inhibition of Evo on xenograft tumor growth is mediated by blocking the NOD1 pathway we detected the levels of NOD1, IκBα, p-P65, p-ERK, p-p38, and p-JNK proteins in xenografted tumors of mice treated with Evo by Western blot analysis." (PMID 30384473, 2018). "Upon injection into a severe combined immune deficiency (SCID) mouse xenograft model, MCF7 cells lacking NOD1 displayed increased estrogen-dependent tumor growth." (PMID 29615116, 2018). "This indicates that NOD1 may have tumour suppressive functions which are at least partially mediated by cells of the haematopoietic compartment." (PMID 28432285, 2017). "Notably, the tumor-promoting effect of NOD1 was significantly mitigated by MARCH7." (PMID 38462600, 2024). "Furthermore, tumour tissues showed significantly decreased expression of cytoplasmic microbial sensors (NOD1 and NOD2) and downstream signaling molecules for innate microbial sensors such as CARD6, CARD9, and TRAF6 (p = 0.0207, p = 0.0040, and p = 0.0119, respectively)." (PMID 37007104, 2023). "Hence, direct targeting NOD1/2 against tumor may result in a therapeutic effect that contradicts expectations." (PMID 37324457, 2023). "Additionally, Kaplan–Meier analysis from both the GSE41258 dataset and Cancer Genome Atlas (TCGA) mRNA‐seq dataset revealed that higher NOD1 expression in tumours was associated with decreased overall survival (OS) rates, suggesting a poor prognosis for patients with CRC and high levels of NOD1." (PMID 36068649, 2022). "Moreover, NOD1 overexpression halted estrogen-dependent tumor proliferation." (PMID 29615116, 2018). "Therefore, NOD1 has been proposed to act as a tumor suppressor gene in ER-positive cells." (PMID 29615116, 2018). "Interestingly, SCID mice grafted with NOD1 overexpressing cells exhibited rapid tumor regression." (PMID 25071785, 2014). "Mechanically, L. intestinalis ameliorates tumorigenesis by stimulating tumor cells to secrete CCL5 and recruiting DC in the TME by the NOD1/NF-κB signaling pathway." (PMID 39773173, 2025). "Mechanistically, L. intestinalis initiated tumor cells to secrete CCL5, a chemotactic factor for DC, through activation of the NOD1/NF-κB signaling pathway." (PMID 39773173, 2025). "Our analysis also showed that anti-tumor effect of CALU is related to the activation of the ubiquitin system and inhibition of the Nucleotide-Binding Oligomerization Domain 1/2 (NOD1/2) and PKA pathways." (PMID 38970088, 2024).